RN7SL799P (RNA, 7SL, cytoplasmic 799, pseudogene)
Gene: Miscellaneous RNA gene on chromosome X (64,210,691 to 64,210,988, forward strand). Ensembl gene ENSG00000244006.
Homologues: Orthologues: chimpanzee Metazoa_SRP (98% identical), macaque Metazoa_SRP (96% identical). Paralogues in human: RN7SL3 (85% identical), RN7SL1 (85% identical), RN7SL2 (84% identical), RN7SL45P (82% identical), RN7SL230P (81% identical), RN7SL509P (81% identical), RN7SL712P (81% identical), RN7SL566P (81% identical), RN7SL278P (81% identical), RN7SL664P (81% identical), RN7SL126P (80% identical), RN7SL597P (80% identical), and 702 more.